WDR45 (WD repeat domain 45)
Diseases named in the same sentence as WDR45 in open-access papers (continued):
Sharing a sentence is not in itself a finding about the gene and the disease.
hypoparathyroidism (1 paper, 2024). Hypoparathyroidism is an endocrine disorder in which the parathyroid glands in the neck do not produce enough parathyroid hormone (PTH). "The proband’s sister had a p.Trp329Gly missense in GATA3, linked to hypoparathyroidism, sensorineural deafness, and renal dysplasia; his daughter had a p.Ser251del in WDR45, associated with beta-propeller protein-associated neurodegeneration." (PMID 39062799, 2024).
Tremor (1 paper, 2021). An unintentional, oscillating to-and-fro muscle movement about a joint axis. "A modified SHIRPA analysis revealed that both male and female mutants were more prone to show tremors with significant differences at 20 months of age (number of animals with tremor: 10/10 Wdr45−/−, 8/10 Wdr45−/+, and 10/10 Wdr45−/Y vs 4/10 Wdr45+/+ and 6/10 Wdr45+/Y; Fisher’s Exact test)." (PMID 34043061, 2021).
X-linked dominant disease (1 paper, 2025). X-linked dominant form of disease. "Loss-of-function mutations in the WD repeat domain 45 (WDR45) gene, which encodes WIPI4, lead to β-propeller protein-associated neurodegeneration (BPAN), a rare X-linked dominant disease characterized by neurodegeneration and brain iron accumulation." (PMID 40079405, 2025).
neurodegenerative disease (10 papers, 2017 to 2025). A disorder of the central nervous system characterized by gradual and progressive loss of neural tissue and neurologic function. "BPAN is a devastating neurodegenerative disease linked to mutations in WDR45 located on the X chromosome." (PMID 40092065, 2025). "Three proteins, WIPI2, WDR45B, WDR45, are already associated with Mendelian neurodegenerative diseases." (PMID 36157071, 2022). "Prior functional analysis of mutated WDR45 has provided evidence of increasing autophagy dysfunction and resultant neurodegenerative diseases." (PMID 29075622, 2017). "Static encephalopathy of childhood with neurodegeneration in adulthood (SENDA)/β-propeller protein-associated neurodegeneration (BPAN) (OMIM #300894) is a neurodegenerative disease caused by a de novo mutation of WD repeat domain 45 (WDR45) located on Xp 11.23." (PMID 36751498, 2022). "In this study, we have uncovered the molecular mechanisms underlying the contribution of WDR45-deficiency to axonal degeneration, revealing intricate relationships between tubular ER dysfunction, phospholipid metabolism, BPAN and other neurodegenerative diseases." (PMID 37292937, 2023). "Given that three β-propeller proteins are now associated with neurodegenerative diseases, the term BPAN may not be appropriate, and it might better be replaced with X-linked neurodegeneration with brain iron accumulation (X-linked NIBA) to describe WDR45-related disorder." (PMID 36157071, 2022).
neurodevelopmental disorder (5 papers, 2017 to 2025). A behavioral and cognitive disorder with onset during the developmental period that involves impaired or aberrant development of intellectual, motor, or social functions.
cancer (3 papers, 2020 to 2024). A tumor composed of atypical neoplastic, often pleomorphic cells that invade other tissues. "Given that mutations of WIPI4 result in reduced stability of the protein in patients with BPAN1, we first depleted WIPI4 using small interfering RNA (siRNA) targeting WD repeat domain 45 (WDR45) to mimic the disease condition in cultured cancer cell lines." (PMID 38454050, 2024).
neurological disorder (3 papers, 2020 to 2021). "Pathogenic variants in the WDR45 (OMIM: 300,526) gene on chromosome Xp11 are the genetic cause of a rare neurological disorder characterized by increased iron deposition in the basal ganglia." (PMID 34043061, 2021).
mitochondrial disease (1 paper, 2023). "Together with the inheritance pattern, which is not suggestive of mitochondrial disease, and the positive findings concerning WDR45, the possibility of a mitochondrial disease is less likely." (PMID 37819743, 2023).
WDR45 also shares sentences with these, for which no sentence is quoted: Epileptic encephalopathy (3 papers); dementia (2); 22q11.2 deletion syndrome (1); adenocarcinoma (1); Angelman syndrome (1); autosomal recessive cerebellar ataxia (1); breast carcinoma (1); Cerebellar atrophy (1); ciliopathies (1); clear cell renal carcinoma (1); Coffin-Siris syndrome (1); Doose syndrome (1); El-Hattab-Alkuraya syndrome (1); Facioscapulohumeral muscular dystrophy type 2 (1); genetic disease (1); Genetic neurodegenerative disease (1); Glass syndrome (1); hereditary spastic paraplegia (1); intellectual disability syndrome (1); KBG syndrome (1); movement disorder (1); muscular disorders (1); Nicolaides-Baraitser syndrome (1); protein folding disorders (1); renal dysplasia (1); Schuurs-Hoeijmakers syndrome (1); Seizure (1); Spasticity (1); Wiedemann-Steiner syndrome (1).